ENSG00000285942 (novel protein)
Gene: Protein-coding gene on chromosome 15 (42,497,395 to 42,548,786, reverse strand). Ensembl gene ENSG00000285942.
Genetic constraint (gnomAD): Missense variants: 221 observed, 276.73 expected, observed/expected ratio (o/e) 0.8, 90% interval 0.71 to 0.89. Synonymous variants: 102 observed, 115.64 expected, observed/expected ratio (o/e) 0.88, 90% interval 0.75 to 1.04.